IL6 (interleukin 6)
Diseases named in the same sentence as IL6 in open-access papers (continued):
Sharing a sentence is not in itself a finding about the gene and the disease.
COVID-19 (continued). "IL-6 is a well-established pro-inflammatory cytokine that contributes to the inflammatory cascade, a hallmark of acute COVID-19 patients, particularly in patients requiring advanced respiratory support or critical care." (PMID 41585373, 2025). "High levels of both IL-6 and IL-10 were found in critically ill COVID-19 patients, which were at the highest risk of death." (PMID 40508859, 2025). "Recent evidence confirms IL-6 as a predictor of severity and death in critically ill COVID-19 patients, suggesting its use for early risk assessment." (PMID 41012595, 2025). "Meanwhile, in COVID-19, overexpression of IL-6 in the lungs causes interstitial pneumonia, multiorgan damage, and risk of death." (PMID 41009326, 2025). "During the acute phase of infection, severe COVID-19 is associated with a “cytokine storm,” characterized by elevated levels of interleukin-6 (IL-6), tumor necrosis factor-alpha (TNF-α), and other inflammatory markers." (PMID 40870365, 2025). "Elevated IL-6 levels are known to be associated with systemic inflammation and worse clinical outcomes in COVID-19." (PMID 40647649, 2025). "In the present study, salivary levels of interleukin-6 (IL-6) were evaluated in patients who attended the COVID-19 Diagnostic Center at the University of Guadalajara and completed a self-reported periodontal disease (Self-RPD) questionnaire." (PMID 40647649, 2025). "Increased IL-6 levels have been consistently associated with disease severity in COVID-19 patients, as have higher concentrations of C-reactive protein, a downstream inflammatory marker." (PMID 40572294, 2025). "This was a larger magnitude of effect than that seen in other diseases where IL-6 signalling is implicated: rheumatoid arthritis (OR 0.54, 95% CI 0.40–0.73); critical COVID-19 (OR 0.66, 95% CI 0.53–0.81); myocardial infarction (OR 0.77, 95% CI 0.66–0.91)." (PMID 40819633, 2025). "Six genes, including TNF, CXCL8, IL-6, IL-1β, IL-2, and IL-10, were associated with three major signaling pathways: the COVID-19 adverse outcome pathway, an overview of pro-inflammatory and pro-fibrotic mediators, and the interleukin-10 signaling pathway." (PMID 40166075, 2025). "In patients with COVID-19, higher levels of IL-6 were associated with more severe inflammation and mortality." (PMID 39779607, 2025). "Increased serum IL-6 and decreased platelet counts are associated with increased severity and mortality in COVID-19 patients." (PMID 40497942, 2025). "In a prospective analysis conducted on clinical trials including patients who were hospitalized with COVID-19, administration of IL-6 antagonists showed a reduction in 28-day all-cause mortality in comparison to traditional treatment or placebo." (PMID 40438117, 2025). "The current study aims to assess the association of COVID-19 severity and mortality with the relative expression of MicroRNA-155 (miR-155) and its association with serum levels of interleukin (IL)-6, IL-10, and their derived ratio." (PMID 41203712, 2025). "It has been established that high levels of IL-6 are associated with greater clinical severity in patients with COVID-19." (PMID 40756075, 2025). "The findings of our research indicated that both COVID-19 and psychosis can cause a cytokine storm, leading to the secretion of large amounts of IL-6." (PMID 40292283, 2025). "A meta-analysis of more than 1400 patients found that IL-6 concentrations were approximately threefold higher in complicated versus uncomplicated COVID-19 and were associated with increased risk of ICU admission and mortality." (PMID 41517263, 2025). "Elevated IL-6 levels contribute to the pathogenesis and severity of COVID-19, which is associated with the prolongation of hospital stay and earlier mortality and increased mortality of COVID-19 patients." (PMID 40115785, 2025). "Contemporary research has established that elevated IL6 expression is a hallmark in the pulmonary tissue of COVID-19 patients." (PMID 41141600, 2025).
COVID-19 (continued). "Recent studies on SARS-CoV-2 revealed that COVID-19-associated cytokine storms (CSs) show elevated levels of IL-1 beta, IL-6, CXCL10, TNF alpha, IFN gamma, MIP 1 alpha, and 1 beta, as well as MCP-1, GM-CSF, VEGF, and IL-10." (PMID 40358160, 2025). "Elevated levels of inflammatory markers, such as LDH, KL-6, ferritin, D-dimer, CRP, and IL-6, as well as decreased lymphocyte counts, have been reported to be associated with poor outcomes in patients with COVID-19." (PMID 40575188, 2025). "High dp-ucMGP and increased IL-6 levels together with low vitamin K levels have been identified as key factors in the inflammatory process and tissue destruction caused by COVID-19." (PMID 39962579, 2025). "Clinical inflammatory markers linked with N protein levels, such as elevated CRP and sustained levels of cytokines like IL-6, have also been associated with prolonged recovery time in COVID-19 patients." (PMID 40872762, 2025). "IL-6 in particular is associated with severe COVID-19 in humans and has been shown to facilitate neutrophil chemoattraction via STAT3 signaling in acute inflammation." (PMID 41279061, 2025). "To validate against known effects of IL6 signaling inhibition, we present associations with rheumatoid arthritis, polymyalgia rheumatica, and severe COVID-19." (PMID 39633572, 2025). "Further analysis showed an overall lower correlation between the cytokines IL-2R, IL-6, IL-7, IL-8, and IL-10 and metabolic phenotype 3 among non-survivors, indicating a lower association of these cytokines with COVID-19-related metabolites." (PMID 41002992, 2025). "This work introducesa novel, rapid, label-free, affinity-enabledelectrochemical sensor for the detection of interleukin-6 (IL-6),a critical proinflammatory cytokine associated with severe conditionslike sepsis and COVID-19." (PMID 40704602, 2025). "IL-6, a key mediator in COVID-19, is associated with myocardial hypertrophy and adverse remodeling due to its pro-fibrotic effects on cardiac fibroblasts." (PMID 40002898, 2025). "Certainly, upregulation of IL-6 is associated with clinical complications during the acute phase of COVID-19, promoting pulmonary fibrosis in the resolution stage of SARS-CoV-2 infection." (PMID 40508959, 2025). "This inflammation, driven by pro-inflammatory cytokines (interleukin-6 (IL-6), IL-1, IL-2, IL-10, tumour necrosis factor alpha, interferon-γ) and coagulation dysfunction, is thought to be the main cause of COVID-19-associated myocarditis." (PMID 40502868, 2025). "We found the IL6 instrument to be associated with a lower risk for severe infections, including pneumonia hospitalization, severe COVID-19 and sepsis." (PMID 40858837, 2025). "Among the most significant results, an association was reported between circulating interleukin-6 and COVID-19 severity in a meta-analysis combining 15 original studies." (PMID 39850833, 2025). "Long-term resistance exercise can reduce levels of inflammatory markers, such as IL-6 and tumor necrosis factor-alpha, which is an important way to alleviate the “cytokine storm” caused by COVID-19." (PMID 41488929, 2025). "Elevated alpha-defensin levels have been associated with thrombotic complications in COVID-19 through interactions with fibrinogen and interleukin-6, highlighting their dual roles in both protective immunity and pathology." (PMID 40904798, 2025). "Supporting this, CSF analysis in several COVID-19-associated ON patients revealed elevated levels of IL-5, IL-6, and IL-8, indicating enhanced innate immune activity." (PMID 40728559, 2025). "The COVID-19-associated cytokine storm, marked by elevated IL-6, IL-1β, TNF-α, and related mediators, upregulates tissue factor and von Willebrand factor expression, while downregulating anticoagulant pathways such as thrombomodulin and protein C." (PMID 40507911, 2025).
COVID-19 (continued). "Recent studies have demonstrated a significant association between elevated IL-6 levels and severe COVID-19 outcomes, indicating that higher IL-6 concentrations correlate closely with increased disease severity and complications." (PMID 40647649, 2025). "Early studies indicated an association between higher levels of IL-6 and increased severity and mortality in COVID-19 patients; however, subsequent evidence has been inconsistent." (PMID 40788382, 2025). "At the same time, those patients infected with COVID-19 exhibited a reduced total number of T cells and increased concentrations of IL-6 and IL-10, which are risk factors that aggravate the severity of COVID-19 in patients with lung cancer." (PMID 39308869, 2024). "Our study further investigated serum levels of CRP, IL-1α, IL-6, and IL-10 as predictive markers for identifying patients at risk of worsening COVID-19." (PMID 39338474, 2024). "Neutrophil–monocyte ratio, neutrophil–lymphocyte ratio, C‐ reactive protein, interleukin 6, and D-dimer were considered to be relevant factors associated with the death risk of COVID-19-related death by LASSO regression." (PMID 39555074, 2024). "Previous research has also highlighted the prognostic and diagnostic utility of IL-6 in pre-operative patients, septic patients and COVID-19 patients." (PMID 39589972, 2024). "Elevated IL-6 levels have been consistently associated with severe disease and cytokine storm phenomena in COVID-19 patients." (PMID 39407725, 2024). "It was shown that miR-142-3p is part of a detrimental regulatory axis with proinflammatory cytokines IL-1β and IL-6 in COVID-19 patients, inducing a response associated with respiratory failure and death." (PMID 39311385, 2024). "Of the 105 cytokines profiled in this study, nine were previously reported to be involved in the cytokine storm associated with COVID-19 including the following: IL-2, IL-4, IL-6, IL-10, G-CSF, IP-10, MCP-1, TNF-α, and IFN-γ." (PMID 39062978, 2024). "This study identified NMR, NLR, CRP, IL6, and DD as factors associated with the risk of COVID-19-related death using LASSO regression." (PMID 39555074, 2024). "Diabetes and atrial fibrillation are clinical factors, and IL-6 and lymphocyte count are laboratory determinants that provide the best predictive model for the assessment of COVID-19 mortality risk." (PMID 38982355, 2024). "Several experimental studies including non-COVID-19 patients reported that IL-6 elevation can increase the risk of deep vein thrombosis through various mechanisms." (PMID 38321099, 2024). "Among the multiple markers analyzed, we observed a significant association between high cellular expression levels of IL-6 and an increased risk of death from COVID-19." (PMID 38601541, 2024). "Circulating levels of various cytokines such as interleukin-6 and tumor necrosis factor are increased in severe COVID-19, and associations with disease severity and outcome have been described." (PMID 38255230, 2024). "This study also shows that liver cirrhosis is associated with lower levels of IL-6, a cytokine often measured to assess COVID-19 severity." (PMID 38791005, 2024). "Conversely, individuals carrying the IL-8 rs2227306T and IL-6 rs1800795C alleles were found to have a reduced risk of severe COVID-19." (PMID 38793070, 2024). "Meta-analyses have further confirmed that, compared to standard treatments and placebos, IL-6 inhibitors can lower the 28-day all-cause mortality in patients with COVID-19-related ARDS." (PMID 39479463, 2024). "Higher IL-6 signal transducer levels, in soluble form, show a suggestive causal effect on severe COVID-19 (0.003 < p < 0.05)." (PMID 39062668, 2024). "A hallmark of early COVID-19 is an increase in pro-inflammatory cytokines, especially IL-6 and TNFα, as well as IL-1 β, IL-8, GM-CSF, and the type 2 inflammatory cytokine IL-13." (PMID 39000027, 2024).
COVID-19 (continued). "COVID-19 patients exhibit markedly elevated levels of pro-inflammatory cytokines (such as IL-6) and chemokines, which are known to be associated with severe pathology and impaired lung function." (PMID 39125989, 2024). "Previous meta-analysis has suggested that IL-6 level significantly elevates in COVID-19 patients and is associated with adverse clinical outcomes." (PMID 38493138, 2024). "Commonly associated with IL-6 secretion, IL-8 levels showed the same tendency as those of IL-6 in COVID-19 patients." (PMID 39583156, 2024). "The first polymorphism (G174C) was confirmed by multiple studies to be positively associated with IL-6 overexpression and subsequent increased systemic inflammation, as well as with pneumonia severity in COVID-19 patients." (PMID 39518964, 2024). "Severe COVID-19 is associated with a cytokine storm characterized by elevated plasma concentrations of interleukins (IL-1ß, IL-2, IL-6, IL-7, IL-8, IL-10 and IL-17), interferons, monocyte chemoattractant protein 1 (MCP-1) and TNF-alpha." (PMID 38732160, 2024). "In this study, they showed that serum levels of IL-6 are significantly increased in the setting of complicated disease of COVID-19 and that elevated levels of IL-6, in turn, are significantly associated with adverse clinical outcomes." (PMID 39118801, 2024). "This inflammatory stress is linked to pro-inflammatory cytokines, notably interleukin-6 (IL-6), which is associated with organ failure among COVID-19 patients." (PMID 38933109, 2024). "Up to our knowledge, our study is the first one to evaluate the role of genetic IL-6 polymorphisms in the prediction of disease severity and clinical outcomes in Egyptian pediatric COVID-19 patients." (PMID 39354444, 2024). "Cytokine storm induced by interleukin-6 (IL-6) has been suggested to potentially cause myocardial injury in COVID-19." (PMID 39395941, 2024). "The inverse association between pre-COVID-19 IL-6 levels and COVID-19 hospitalization/critical illness is in line with the current literature, suggesting the overall protective role of higher IL-6 levels, providing immune readiness." (PMID 39062668, 2024). "Different major dysregulated biosignatures including but not limited to Interferon Alpha 1 (IFNA1), Interferon Alpha Inducible Protein 6 (IFI6), Toll-Like Receptor 4 (TLR4) and interleukin-6 (IL6) are linked to host responses to COVID-19." (PMID 39040605, 2024). "A dramatic increase in IL-6 level has been associated with COVID-19 and appears to significantly impact disease progression compared to that of SDD." (PMID 39583156, 2024). "Inflammatory biomarkers such as C-reactive protein (CRP), neutrophil-to-lymphocyte ratio (NLR), and interleukin-6 (IL-6) have been reported to be associated with the clinical course of COVID-19 during hospitalisation." (PMID 38982551, 2024). "Severe COVID-19 cases have been linked to elevated neutrophil-to-lymphocyte ratios and increased serum levels of neutrophil-associated cytokines such as IL-6." (PMID 38099844, 2024). "Several systematic reviews and meta-analyses revealed that IL-6 inhibitors such as tocilizumab were associated with reduced mortality in patients with COVID-19." (PMID 38394183, 2024). "An example is rs1800795 on the IL-6 gene; the G allele of this variant is associated with lower IL-6 levels and also with a higher risk of severe COVID-19." (PMID 39062668, 2024). "In their meta-analysis, they investigated the risk of thromboembolic events in hospitalized patients with COVID-19 who received different immunomodulatory agents, including IL-6 antagonists such as tocilizumab." (PMID 38321099, 2024). "Elevated levels of IL-6, expression of the cytokine release syndrome, are associated with a complicated and severe course of COVID-19." (PMID 38010585, 2024). "COVID-19 positive individuals with a moderate to severe risk of OSA exhibited lower serum IL-6 levels (median 4, IQR 28) compared to individuals with a mild risk of OSA (median 21, IQR 38, p < 0.05)." (PMID 38476500, 2024).
COVID-19 (continued). "A comparison of HA’s diagnostic utility with other COVID-19 biomarkers revealed that ROC AUC for HA was lower than those for inflammatory markers: IL-6 (0.863 vs. 0.992), CRP (0.863 vs. 0.998), PCT (0.863 vs. 0.966), and ferritin (0.863 vs. 0.922)." (PMID 39685929, 2024). "To fill in this gap, here we extensively investigated the association of genetically instrumented IL-6 pathway components with the risk of severe COVID-19." (PMID 39062668, 2024). "Inflammation was induced in COVID-19 instances, according to recent clinical findings, and this induction was linked to an elevated level of cytokines, such as IL-1, IL-6, IL-10, and TNF." (PMID 38337760, 2024). "This includes positive associations of IFNα c-aAb and male sex—also documented in COVID-19 studies—as well as a positive association of IL-6 c-aAb and female sex." (PMID 39606243, 2024). "Global studies have found that IL-6 has the highest specificity in predicting severe COVID-19 patients and is associated with poor clinical outcomes." (PMID 40376291, 2024). "Previous suggestions have implicated its involvement in the severity of COVID-19, with elevated IL-6 levels being associated with a more severe disease course." (PMID 38783290, 2024). "Based on our findings here, and despite the known effects of IL-6 levels during-COVID-19, higher levels of pre-COVID-19 IL-6 in blood are likely to reduce the risk of developing severe COVID-19." (PMID 39062668, 2024). "Elevated IL-6 is known to be a key player in the cytokine storm associated with severe COVID-19, which can lead to lymphopenia and impaired immune function." (PMID 39407725, 2024). "Given the central role of IL-6 in COVID-19 inflammation and its association with severe disease, we aimed to analyse the behaviour of IL-6 and its soluble receptor complex during different waves of the pandemic." (PMID 39063569, 2024). "IL-6 and TNFα are central to the inflammatory response in COVID-19, and IL-13 has also been linked to disease severity, driving increased levels of eosinophils and macrophages in the lungs and stimulating smooth muscle hypertrophy and fibrosis." (PMID 39000027, 2024). "The genetically instrumented IL-6 signal transducer showed a suggestive positive association with severe COVID-19 (OR (CI 95%) = 1.13 (1.00–1.27), p = 0.04)." (PMID 39062668, 2024). "This biologic agent, which is known for increasing infection risk, was administered when these patients had high IL-6 levels, with the aim of managing the hyperinflammation associated with severe COVID-19." (PMID 39540054, 2024). "Some studies demonstrated consistently higher levels of TNF-α than IL-6 in severe COVID-19 patients and those with underlying comorbidities such as obesity, chronic heart failure, and hypertension." (PMID 39518964, 2024). "The severity of COVID-19 is caused by an excessive release of inflammatory cytokines such as interleukin-6 (IL-6) due to dysregulated innate and adaptive immune systems in the host." (PMID 39125944, 2024). "Background/Objectives: Severe clinical course and mortality from COVID-19 are mostly associated with increased concentrations of IL-6 and IL-10." (PMID 39518552, 2024). "Caspase-1 activation and a predominant IL-1/IL-6 signature associated with IFNγ-induced chemokines remain highly detectable in the BALF of steroid-resistant COVID-19-ARDS, arguing for new multi-targeted therapeutics in COVID-19-ARDS." (PMID 39882243, 2024). "CXCL-10 is associated with IL-6 secretion with raised levels seen in COVID-19 patients with pulmonary immune cell infiltration and cytokine storm." (PMID 39000027, 2024). "IL-6 levels have been closely associated with the severity of pulmonary disease in COVID-19 patients." (PMID 39458339, 2024). "At least 16 (0.3%) encounters during COVID-19 received diagnostic testing for MIS-C as shown by the rates of tests for interleukin-6 and SARS-COV-2 IgG antibody." (PMID 38745831, 2024).